GFAP (glial fibrillary acidic protein)
Diseases named in the same sentence as GFAP in open-access papers (continued):
Sharing a sentence is not in itself a finding about the gene and the disease.
ischemia (continued). "Thus our results demonstrated that the majority of GFAP+ reactive astrocytes resulted from the upregulation of GFAP in existing astrocytes without proliferation, and that the generation of proliferating astrocytes was highly time-dependent during post ischemia." (PMID 24886391, 2014). "We observed a very significant negative association between the blood glucose levels during the period of ischemia and the severity of WMI as measured by GFAP (p < 0.0001; LME) and Iba1 (not shown; p < 0.0001; LME)." (PMID 24416093, 2013). "We found a significant negative association between the cephalic BP measured near the end of ischemia and the severity of WMI as measured by GFAP (p < 0.04), and Iba1 staining intensity (not shown; p < 0.006; LME)." (PMID 24416093, 2013). "Immunohistochemical staining for glial fibrillary acidic protein (GFAP), a marker for astrocytes, was carried out in order to investigate the activation of astrocytes in the CA1 region in the ND and IF groups with or without ischemia." (PMID 33440708, 2021). "In order to investigate the different patterns of astroglial immunoreaction in more detail, immunolabeling of S100β as a further marker for astrocytes were combined with GFAP- and STL-staining in the ischemia-affected neocortex compared to the contralateral, non-affected hemisphere." (PMID 28445478, 2017).
depression (161 papers, 2012 to 2026). "Although plasma GFAP has been associated with clinical depression, the relationship between GFAP and depressive symptoms is unclear." (PMID 41476029, 2026). "To test this, we assessed hippocampal expression of GFAP, an astrocytic marker known to be associated with the pathophysiology of depression and cognitive dysfunction." (PMID 40855793, 2026). "Research on the association between neuron–astrocyte interactions in depression indicates that astrogliosis, characterized by elevated GFAP levels, is correlated with disrupted monoamine signaling." (PMID 40780966, 2025). "We found an interaction between GFAP and CT status, reflecting an inverse association of GFAP with cumulative depression among CT− subjects (adjusted odds ratio = 0.84, 95% CI: 0.77–0.92), but not among CT+ subjects." (PMID 40190352, 2025). "In this analysis of a prospective cohort study of >1500 participants with a ‘mild’ TBI (i.e. presenting GCS of 13–15), lower peripheral GFAP within 24 h of injury was associated with meeting a clinical cut-off for depression within the first year of recovery." (PMID 40190352, 2025). "The purpose of this study was to evaluate the association of day-of-injury (<24 h) GFAP with endorsing depression or SI throughout the first year of recovery from TBI with Glasgow Coma Scale (GCS) 13–15." (PMID 40190352, 2025). "Astrocyte activation, marked by increased expression of GFAP, is a hallmark of neuroinflammation and is often observed in various neurological and psychiatric disorders, including depression." (PMID 40332038, 2025). "We also explored interactions between GFAP levels, head computed tomography (CT) findings and pre-injury depression/SI risk factors (e.g. history of psychiatric disorders or prior TBI) on the cumulative prevalence of depression and SI." (PMID 40190352, 2025). "Higher NfL levels were found to be associated with major depression, while higher GFAP levels were associated with schizophrenia." (PMID 39054505, 2024). "Elevated GFAP levels were positively associated with a greater psychiatric symptom burden, specifically anxiety/depression scores, a finding that is congruent with previous reports of elevated GFAP levels in CSF in patients with major depression." (PMID 39048548, 2024). "The significant association between depressive symptoms and increased GFAP levels emphasizes the need for clinicians to actively monitor SCGs for signs of depression." (PMID 39297507, 2024). "Astrocyte activation, reflected in higher levels of CSF GFAP, was associated with worse depression and apathy in PWH." (PMID 37205974, 2022). "This study’s principal finding that depression in PWH was associated with higher CSF GFAP levels was robust to consideration of a variety of important demographic and disease-related potential confounds." (PMID 37205974, 2022). "Post-mortem investigations have implicated cerebral astrocytes immunoreactive (-IR) for glial fibrillary acidic protein (GFAP) in the etiopathology of depression and suicide." (PMID 33613346, 2021). "A reduction in GFAP-positive astrocytes in the hippocampus and prefrontal cortex is associated with major depressive disorder." (PMID 33109198, 2020). "Moreover, we found that SNS reversed WIRS‐induced GFAP loss and cellular senescence, which are major pathological hallmarks associated with depression and memory decline in the hippocampus of mice." (PMID 40855793, 2026). "However, after additionally adjusting for antidepressant use and history of depression, only the association between plasma GFAP and depressive symptoms remained." (PMID 41476029, 2026). "Notably, prior work reported that levels of GFAP are positively associated with age at the onset of depression among individuals aged 34 to 86 years." (PMID 41476029, 2026). "Elevated GFAP has been associated with brain amyloid deposition, and with depression." (PMID 41476029, 2026).
depression (continued). "Based upon the results of prior research, we hypothesized that mild TBI patients (GCS 13–15) with lower GFAP levels on the day of injury would have a higher risk of endorsing depression or SI in the first year." (PMID 40190352, 2025). "Multivariable logistic regression models were used to assess the association of day-of-injury GFAP levels with year 1 CI of depression or suicidal ideation adjusting for age, sex, prior TBI, psychiatric history and acute intracranial trauma on head computed tomography (CT) scan." (PMID 40190352, 2025). "Furthermore, in subjects with long COVID-19 and post-acute neurological complications, anxiety and depression were significantly associated with higher serum glial reactivity, marked by elevated neuroglial GFAP and Neurofilament Light Polypeptide (NFL) scores." (PMID 39451987, 2024). "Further exploration showed that miR-21 was correlated with mRNA of myelin proteins, astrocytic GFAP, and oligodendrocyte-associated transcription factors while the specific mechanism of miR-21 in white matter alterations in depression still should be further investigated." (PMID 38023826, 2023). "Decreased levels of GFAP protein in key brain regions such as the cortical, limbic system and hippocampus in patients with depression may be the critical cause of astrocyte and neuronal apoptosis, as well as specific brain changes in the brain." (PMID 33192662, 2020). "Stress-based models of depression are associated with a reduction in GFAP expression." (PMID 33109198, 2020). "Acupuncture on PC6 has a therapeutic effect on depression and anxiety and can relieve the damage of astrocytes caused by chronic stress and play an antidepressant role possibly by upregulating the expression of GFAP in prefrontal cortex." (PMID 30854008, 2019). "However, reduced GLT1 and GFAP expression have been associated with several psychiatric disease models, including anxiety, stress, or depression." (PMID 31998080, 2019). "In the current study, we found an association between GFAP and depressive symptoms among older adults that remained after adjusting for sociodemographic and lifestyle factors, chronic conditions, general cognition, history of depression, and antidepressant use." (PMID 41476029, 2026). "A consistent decrease in GFAP expression has been found in the frontal cortex tissue of major depressive disorder patients, and there is evidence that decreased GFAP expression in corticolimbic regions may be a common neurobiological deficit associated with depression." (PMID 39000602, 2024). "Therefore, GFAP could be the focus of subsequent studies on the association between depression and astrocytes and become a new potential target for antidepressant drugs to act." (PMID 37108148, 2023). "Based on existing knowledge, a causal link between astrocyte activation, as indexed by CSF GFAP, and depressed mood is plausible; however, it is conceivable that changes in activity, diet and other lifestyle factors associated with depression might lead to astrocyte activation (reverse causation)." (PMID 37205974, 2022). "We further included quantification of the number of GFAP-positive astrocytes, as these glia cells have been implicated in the pathogenesis of affective disorders and were found to be reduced after stress in animal models and in patients suffering from depression." (PMID 23049985, 2012). "Reduced GFAP staining has also been reported in the hippocampi of patients with depression, particularly in the DG of women with major depressive disorder, with a similar trend observed in the CA2/3 region." (PMID 40855793, 2026). "Chronic unpredictable stress reduced GFAP‐expressing astrocyte density in the prefrontal cortex of rats, inducing depression‐like behavior." (PMID 40855793, 2026). "GFAP levels were seven times lower in younger (aged < 60 years) individuals with major depressive disorder than those in older patients and age‐matched controls." (PMID 40855793, 2026).
depression (continued). "In a chronic unpredictable stress (CUS)-induced depression rat model, the expression of glial fibrillary acidic protein (GFAP) and BDNF was reduced in the hippocampus; however, gastrodin reversed these changes." (PMID 40371076, 2025). "In our study, XCHT was proven to alleviate depressive disorders by downregulation of IL‐1β, TNF‐α, and IL‐6 inflammasome, modulating the immune system by inhibiting Iba‐1 and GFAP overexpression, making it a promising candidate for the treatment of depression." (PMID 39981856, 2025). "This suggests an interaction between CT status and GFAP levels on the cumulative depression outcome." (PMID 40190352, 2025). "Of 5349 keywords, the top 10 frequent keywords are astrocyte, depression, microglia, hippocampus, neuroinflammation, glia, inflammation, glutamate, cytokine, and GFAP." (PMID 40108901, 2025). "Another important fact is the age of the patients and the onset of depression, that can affect the reduction of packing density of GFAP expression." (PMID 40650814, 2025). "In contrast, older patients with a late-onset depression showed increased GFAP-IR and cell density in dorsolateral PFC, pointing out the importance of age in MDD onset for its prognosis." (PMID 40650814, 2025). "Our results demonstrate that Venlafaxine is more effective than BAY K 8644 in ameliorating depression like behaviors and increasing Dnmt3a expression while decreasing GFAP expression." (PMID 39268349, 2024). "Omega‐3‐depleted red blood cell membranes and increased GFAP levels have been reported in patients with depression or depressive symptoms." (PMID 38877658, 2024). "Accumulating evidence supports a key role of GFAP in detecting the possibility of major depressive disorder (MDD)." (PMID 38216970, 2024). "GFAP concentrations in the cerebellum, prefrontal cortex, hippocampus, and anterior cingulate cortex have been reported to decrease in patients with major depression compared to controls." (PMID 38990919, 2024). "Within the statistically significant linear regression models, the R2 values ranged from 0.06 to 0.25, implying that additional variables beyond depression, cognitive T-scores, and age likely influence changes to mitochondria and GFAP signal measures." (PMID 39175522, 2024). "Otherwise, glial dysfunction with reduced hippocampal GFAP expression levels was previously reported in preclinical depression models of chronic psychosocial stress." (PMID 38732053, 2024). "Preclinical studies using animal models of depression have consistently shown a decrease in the number and expression of cells expressing S100B and GFAP, including in the hippocampal dentate gyrus (DG)." (PMID 38783266, 2024). "Changes in depression among SCGs were significantly correlated with increased GFAP levels (p = .003), indicating that greater depressive symptoms during caregiving are associated with increased neuroinflammation." (PMID 39297507, 2024). "Some studies also evaluated NfL and GFAP in the blood as potential markers for primarily psychiatric disorders such as depression or schizophrenia." (PMID 39054505, 2024). "Research has demonstrated that serum GFAP levels correlate with depression severity, offering a potential biomarker for evaluating treatment efficacy and disease progression." (PMID 39796043, 2024). "The findings also showed that vitamin D3 significantly alleviated anxiety- and depression-like behaviors, reduced the expression level of GFAP, and increased BDNF and neuronal protection by inhibiting the overactivation of astrocytes." (PMID 39135986, 2024). "Research has shown increased GFAP levels in the cerebrospinal fluid and blood of patients with depression, indicating astrocytic activation, which is a feature of depression." (PMID 39297507, 2024). "Clinical studies have shown that the use of venlafaxine can reduce GFAP levels in the cerebrospinal fluid of patients with depression, consistent with our staining results." (PMID 39268349, 2024).
depression (continued). "Lastly, depressed patients have shown elevated levels of extracellular vesicles containing GFAP or those co-expressing AQP4 and GFAP in serum samples, providing additional evidence for the existence of astrocyte dysfunction in depression." (PMID 39451987, 2024). "Reductions of astroglia expressing glial fibrillary acidic protein (GFAP) are consistently found in the prefrontal cortex (PFC) of patients with depression and in rodent chronic stress models." (PMID 37461693, 2023). "Mice in depression models such as chronic unpredictable mild stress (CUMS) showed decreased GFAP+ cell density, while riluzole reversed decreased GFPA mRNA expression and promoted astrocyte metabolism in CUMS mice." (PMID 37063256, 2023). "Both animal and clinical studies on depression have shown there is decreased GFAP together with increased neuroinflammation as seen by the expression of Erk1/2, p-p38 MAPK, and NF-κB." (PMID 37296570, 2023). "Strong evidence shows that a decrease in hippocampal astrocytes, GFAP expression, GFAP-immunoreactive astrocytes, and astrocyte density is related to depression." (PMID 35250485, 2022). "Depression also shows a decrease in GFAP immunoreactivity in the dentate gyrus, which was related to a decrease in BDNF expression." (PMID 35625676, 2022). "It has been reported that the area fraction of GFAP-immunoreactivity in the hippocampal CA2/CA3 subregions is negatively correlated with the duration of depression in suicide victims." (PMID 35250485, 2022). "Previous studies demonstrated that nerve factors like GFAP and NE levels were closely related to patients' depression." (PMID 35401732, 2022). "It was shown that the 8-OHdG and GFAP expression level was increased due to an increase in inflammation and oxidative stress level in major depressive disorder." (PMID 35207733, 2022). "Many clinical studies have shown that the expression of GFAP is significantly reduced in the brains of patients with generalized depression and depressive disorder." (PMID 35530016, 2022). "The differences in GFAP levels between patients suffering from depression (632.26 ± 309.18) and controls (245.56 ± 176.25) remained highly significant (T = 6.698, p < 0.001)." (PMID 34021122, 2021). "Our findings also support post-mortem studies on depression which have found semi-qualitative decreases in the number of GFAP-IR astrocytes in other brain regions, such as the hippocampus." (PMID 33613346, 2021). "Meanwhile, autophagy agonist Rap enhanced the promotion of Ori on GFAP expression, while autophagy inhibitor 3-MA abolished the protective role of Ori on astrocytes in the depression models, indicating that Ori can protect astrocytes by enhancing autophagy." (PMID 35096901, 2021). "A reduction in GFAP-IR astrocyte density in multiple brain regions from depressed suicides supports a strong consensus in the literature for decreased regional GFAP protein levels in post-mortem studies and animal models of depression." (PMID 33613346, 2021). "The main finding of the current study was that the GFAP concentration in the CSF was significantly higher in patients with unipolar depression than in controls with IIH." (PMID 34021122, 2021). "The concentrations of glial fibrillary acidic protein (GFAP) in the cerebellum, prefrontal cortex, and anterior cingulate cortex have been found to be lower in patients with depression than in healthy controls." (PMID 34021122, 2021). "Certainly, data indicating a possible role of GFAP in the pathogenesis or progression of major depression will add to the growing knowledge of the possible involvement of inflammatory processes in depression." (PMID 34021122, 2021). "As only very limited data about the relation of GFAP in CSF to unipolar depression are currently available, this study can provide a starting point for further investigations." (PMID 34021122, 2021).